BDNF (brain derived neurotrophic factor)
Diseases named in the same sentence as BDNF in open-access papers (continued):
Sharing a sentence is not in itself a finding about the gene and the disease.
Cognitive impairment (continued). "However, oral administration of NK210, NK219, or Mx decreased cognitive impairment-like behaviors, NF-κB+/Iba1+ cell population, and IFN-γ and TNF-α expression in the hippocampus, while BDNF+/NeuN+ cell population and IL-10 expression increased." (PMID 34667205, 2021). "It revealed that a single session of brain yoga significantly improved the short-term memory of middle-aged women and increased serum BDNF levels especially in women without a mild cognitive impairment." (PMID 34070377, 2021). "Three further markers were non-significantly (P < 0.1) higher in participants without cognitive impairment (BDNF, TNF-β, Mip-1β)." (PMID 36043690, 2021). "By increasing BDNF levels, EPCs may mitigate the neurological complications of epilepsy, as well as neuropsychiatric comorbidities like anxiety, PTSD, and cognitive impairments." (PMID 33815100, 2021). "BDNF rs56164415 T alleles were more frequently found in subjects with PTSD, smokers and non-smokers, with impaired cognition, i.e., with the higher PANSS cognition subscale scores and with the lower ROCF immediate recall test scores." (PMID 33926045, 2021). "Subsequently, a binary logistic regression analysis was used to evaluate the potential for plasma concentrations of BDNF to discriminate between patients with cognitive impairment from those without cognitive impairment." (PMID 34341419, 2021). "The ADSCs also secreted neurotrophic factors like BDNF, NT3, and NT4, which may play a role in alleviating cognitive impairments accompanying epilepsy." (PMID 33815100, 2021). "BDNF treatment post-TBI in mice induced significant improvement in cognitive impairment when compared with TBI mice that did not receive treatment." (PMID 32754029, 2020). "Finally, KD inhibition of histone deacetylase can allow the expression of proteins improving cellular homeostasis and function (brain-derived neurotrophic factor (BDNF)), and in turn cognitive deficit in AD patients." (PMID 33003562, 2020). "Previous studies show that the upregulation of BDNF and NT3 improves cognitive function in AD, suggesting that CK administration may be able to prevent cognitive impairment." (PMID 32210026, 2020). "Our previous study indicated that aerobic exercise relieves cognitive impairment in patients with vascular cognitive impairment (VCI) via regulating brain-derived neurotrophic factor (BDNF), but the mechanism is not yet clear." (PMID 33213523, 2020). "The relation between LPA species and BDNF is interesting in plasticity and neurogenesis functions, their involvement in AUD might serve as a biomarker of cognitive impairment." (PMID 33051508, 2020). "Considering the fact that similar levels of BDNF were seen in both conditions but cognitive performance was suppressed in hypoxia, acute elevation of BDNF did not compensate for hypoxia-induced cognition impairment." (PMID 32759658, 2020). "None of the three studies analyzed the relationship between BDNF and cognitive impairment in PD patients." (PMID 31365694, 2019). "Previous researches suggested that decreased BDNF and increased DPP4 activities were found in the periphery circulation of patients with MCI, suggesting that BDNF and DPP4 activity might both play a pathogenetic role in the development of cognitive impairment." (PMID 30886577, 2019). "Notably, early clenbuterol treatment alleviated sepsis-induced cognitive deficits by polarizing microglia toward an anti-inflammatory phenotype, reducing proinflammatory cytokines including IL-1β, TNF-α, and up-regulating CREB/BDNF, PSD95, and GluN2B." (PMID 31354429, 2019). "Moreover, AAL extract treatment exerted memory-enhancing effects via inhibition of the BDNF/pCREB and Akt signaling pathways in SCO-induced cognitive deficit mice." (PMID 31331043, 2019). "Besides, sepsis mice also exhibited increasing neuroinflammation, down-regulated CREB/BDNF, decreasing PSD95 and GluN2B expression, and displayed hippocampus-dependent cognitive impairments." (PMID 31354429, 2019).
Cognitive impairment (continued). "Accordingly, BDNF administration or lack of pro-insulin resistance gene p66Shc in mothers abolishes the HFD-dependent transmission of cognitive impairment to the offspring." (PMID 31641124, 2019). "We assessed whether anaesthesia and surgery could downregulate BDNF in the hippocampal dorsal CA1 area and whether laparotomy under inhalation anaesthesia in middle-aged mice was a well-established postoperative cognitive impairment model." (PMID 31708739, 2019). "Bilateral intrahippocampal infusion of GQ1b, when administered after disease progression, restores cognitive impairments in 3xTg-AD mice accompanied by an increase in BDNF, but not NGF or NT-3 levels." (PMID 31186474, 2019). "Taken together, these results suggest that gain beyond baseline levels of BDNF and PSD95 may serve to increase the synaptic strength of neurons, thereby contributing to the rescue of cognitive deficits." (PMID 29749079, 2018). "Furthermore, naringin (Nrg) substantially prevented cognitive impairment in MHE/DA-treated rats and upregulated the Shh pathway, paralleling the elevated expression of BDNF/NT3." (PMID 28840059, 2017). "We have observed a statistically significant change in plasma BDNF levels over time post-chemotherapy, and such observation was relevant in both self-perceived cognitive impaired and non-impaired subgroups." (PMID 29258453, 2017). "To investigate whether amelioration of cognitive impairment in ApoE-KO mice correlated with 7,8-DHF treatment, we assessed the alteration of BDNF/TrkB/AKT pathway with western blotting." (PMID 27965573, 2016). "A total of 110 participants without subjective or objective cognitive impairment underwent BDNF genotyping." (PMID 26496261, 2015). "Indeed, in this study apoE-related cognitive impairment correlates with a decrease in the levels of NMDR subunits and components of the signaling pathway (p-CaMK-II/p-CREB/BDNF)." (PMID 25871877, 2015). "The canine model provides us with an opportunity to test the relationship between cognitive impairment in aging, related to a decrease in BDNF serum levels, and the effects of non-pharmacological interventions." (PMID 26464952, 2015). "Due to this limitation, the possibility that intracranial injections of BDNF improve cognitive performance in LPS-induced cognitive impairment animal models was not investigated." (PMID 24520281, 2014). "Thus, a previous study suggested a close correlation between reduced expression of BDNF and CREB in the hippocampus with cognitive impairment." (PMID 25231482, 2014). "The observed cognitive impairment in minipigs fed the HFLC and LFHS diets could thus indicate that other pathways, beside those involved in regulation of BDNF and circulatory inflammation might be responsible for the observed effects." (PMID 24223947, 2013). "An imbalance in the conversion of proBDNF to BDNF can significantly affect cognitive function and accelerate the progression of neurodegenerative diseases, but its relevance in the setting of chronic GH/IGF‐1 excess and cognitive impairment in acromegaly remains largely unexplored." (PMID 41550023, 2026). "In obesity (OB) and type 2 diabetes mellitus (T2DM), dysregulated myokine profiles characterized by reduced levels of irisin, brain-derived neurotrophic factor (BDNF), and cathepsin B (CTSB) have been reported and may contribute to the development of both sarcopenia and cognitive impairment." (PMID 41305665, 2025). "Additionally, this study did not assess BDNF gene expression in specific diseases such as Alzheimer’s disease or cognitive impairment." (PMID 41146751, 2025). "Although the mechanism and influence of TRF on cognitive impairment and neurological damage are controversial, the present study certified that TRF enhanced spatial memory ability, decreased Aβ deposition, promoted the recruitment of microglia to plaques, and increased BDNF level in AD mice." (PMID 40236783, 2025).
Cognitive impairment (continued). "Therefore task state fNIRS combined with the expression of BDNF and NGF factors in peripheral blood can be considered as a promising biomarker of cognitive deficits after stroke, which can predict the therapeutic response for the modulation of functional brain networks in PSCI." (PMID 40948655, 2025). "Thus, the cholinergic system homeostasis and BDNF signaling transmission might contribute to suppressing neuroinflammation through inhibition of NF-κB pathway and IBA-1, thereby alleviating cognitive impairment in aging mice after SCH supplementation." (PMID 40509464, 2025). "BDNF is a well-established regulator of synaptic plasticity, particularly in the hippocampus, where it supports the induction and maintenance of LTP.The reduction in BDNF expression observed in our study likely contributes to the impaired synaptic function and cognitive deficits seen in AH mice." (PMID 40354376, 2025). "Furthermore, the serum BDNF levels had a decreasing tendency in T2DM patients with cognitive impairment compared with those without cognitive impairment." (PMID 38648255, 2024). "Moreover, patients with an earlier age of onset exhibit more negative symptoms and cognitive deficits, correlating with lower serum BDNF levels." (PMID 39408997, 2024). "Therefore, our study aims to explore the alteration tendency of the serum BDNF levels in T2DM patients with or without cognitive impairment using meta-analysis with a comprehensive evaluation of relevant literature." (PMID 38648255, 2024). "Thus, the reduction of BDNF might contribute to the neuropathophysiology of brain damage in T2DM, especially relating to cognitive impairment in T2DM." (PMID 38648255, 2024). "This study demonstrated that reduced SIRT1/BDNF expression, impaired synaptic plasticity, and decreased neuronal excitability were observed in glutamatergic neurons in the CA1 region of mice after anesthesia/surgery, accompanied by significant cognitive impairment." (PMID 38783169, 2024). "In fact, in neurodegenerative disorders such as multiple sclerosis, Alzheimer’s disease, mild cognitive impairment, and Parkinson’s disease, which are related to lower levels of brain-derived neurotrophic factor, the role of physical exercise vs. no exercise has been investigated." (PMID 38610829, 2024). "Indeed, our results are in agreement with other studies in which high-caloric diets did not induce alterations in BDNF levels, even in the presence of cognitive impairment." (PMID 38791562, 2024). "Besides, T2DM cognitive impairment group had a slightly lower serum BDNF level compared to the non-cognitive impairment group (SMD: -2.59, z = 1.87, P = 0.06)." (PMID 38648255, 2024). "However, BDNF has been proposed as a broad biomarker of several neuropsychiatric disorders that are highly comorbid with AUD and/or cognitive impairment, especially depression, posttraumatic stress disorder, schizophrenia, cocaine use disorder, Parkinson’s disease and Alzheimer’s disease." (PMID 36674698, 2023). "Brain-derived neurotrophic factor (BDNF) is a key molecule in promoting neurogenesis, dendritic and synaptic health, neuronal survival, plasticity, and excitability, all of which are disrupted in neurological and cognitive disorders such as Alzheimer's disease (AD)." (PMID 38002258, 2023). "These negative effects could subsequently aggravate cognitive impairment through neurodegeneration, reduced brain-derived neurotrophic factor generation, and the deposition of amyloid beta plaques." (PMID 36833763, 2023). "Decreased BDNF levels represent a lack of trophic support and may contribute to cognitive impairment in Alzheimer’s disease." (PMID 37371860, 2023). "However, an increase in the BDNF did not prevent cognitive impairment under hypoxia, as measured by choice reaction time (CRT) and the number of correct reactions (NCR)." (PMID 37559758, 2023). "However, the mediator role of BDNF in the pathology of cognitive impairment in diabetes was not determined." (PMID 36936159, 2023).
Cognitive impairment (continued). "T2DM patients without cognitive impairment displayed reductions in IL 4 and BDNF levels, as well as significant alterations in their SBM indices, indicating that prior to the emergence of cognitive impairment, the SBM indices, peripheral cytokines, and BDNF may have altered in T2DM patients." (PMID 37113152, 2023). "In conclusion, in this study, plasma BDNF was positively correlated with cognitive symptoms only in the subgroup of patients with a cognitive deficit, but not in the subgroup of patients with a normal cognitive score, nor in the control group of healthy subjects." (PMID 37445746, 2023). "In the present study, we aimed to investigate new potential biomarkers of neurodegeneration that could predict cognitive impairment in SUD patients: the circulating concentrations of Neurofilament Light chain protein (NfL) and Brain-Derived Neurotrophic Factor (BDNF)." (PMID 36674698, 2023). "We observed that repeated administrations of BDNF-eMSCs (5 × 105 cells per administration) into the cerebroventricular cavity of rats after TBI led to significant protective effects against neuronal death, neurological deficits, and cognitive impairment following TBI." (PMID 36986535, 2023). "In summary, we can tentatively conclude that AE may improve cognitive impairment in T2DM mice by upregulating MALAT1 expression in serum-exosomes, competitively inhibiting miR-382-3p, and upregulating BDNF expression, thereby inhibiting hippocampal neuron apoptosis." (PMID 37740187, 2023). "Therefore, we aimed to study the relation between plasma BDNF levels and cognition in two separate groups of schizophrenic patients with different cognitive statuses: with and without a cognitive deficit." (PMID 37445746, 2023). "Although proBDNF evaluation was not included in previous studies, we have shown that mature BDNF may play a critical role in PND because mature upregulation of BDNF by neuroprotective agents can rescue cognitive impairment after surgery and anesthesia." (PMID 37735415, 2023). "Interestingly, exercise-induced elevated BDNF levels did not prevent cognitive impairment in the E group under both normoxia and hypoxia conditions." (PMID 37559758, 2023). "Our results support a significant role for BDNF in the cognitive functioning of schizophrenics with some degree of cognitive deficit, but suggest that BDNF may not be crucial in patients with a normal cognitive status." (PMID 37445746, 2023). "The main aim of this study was to compare the levels of BDNF and tyrosine kinase receptor B (TrkB) in normal children and those with obstructive sleep apnea (OSA) and primary snoring (PS) and to explore a possible link between BDNF/TrkB, inflammation, and SDB with cognitive impairment in children." (PMID 36683819, 2022). "We may hypothesize that FM symptoms of cognitive impairment and depressive mood are mediated by a lack of BDNF." (PMID 35832286, 2022). "A meta-analysis indicated that AD patients, rather than mild cognitive impairment patients, have significantly lower serum BDNF levels compared to age-matched healthy controls, and a significant decrease in peripheral BDNF levels can only be detected at the late stage of dementia." (PMID 36158555, 2022). "However, exposure of aged mice to 3% sevoflurane led to significant cognitive impairment, which may be due to the inhibition of AHN probably through the BDNF/TrkB and NT-3/TrkC pathways." (PMID 35309893, 2022). "Moreover, GL or HE could modulate BDNF/CREB/ERK in the brain and attenuate cognitive deficits in an amnesia mouse model." (PMID 35126824, 2022). "Taken together, our theory relies on that mood and cognitive disorders reported at this present work may involve other pathophysiological mechanisms but not BDNF via." (PMID 36329802, 2022). "In non-responders, the rise in BDNF is positively correlated with more severe cognitive impairment." (PMID 36248031, 2022).
Cognitive impairment (continued). "However, no clinical studies are confirming the relationship between BDNF and cognitive impairment in children with SDB, nor relevant research about detailed stratified analyses of PS and OSA in children." (PMID 36683819, 2022). "Ovarian hormone fluctuations during the luteal phase, such as decreased estrogen and elevated progesterone, can induce brain GABA and BDNF changes, which may ultimately contribute to PMS behavioral complaints such as sleep disturbance and mood and cognitive disorders." (PMID 36699021, 2022). "Moreover, a negative correlation between decreased BDNF and increased severity of cognitive impairment has been observed." (PMID 35269761, 2022). "Not yet been investigated, brain-derived neurotrophic factor (BDNF) may be involved in cognitive impairments of LLS." (PMID 34239458, 2021). "Moreover, BDNF was able to improve the cognitive impairments induced by MPTP in mice based on the open filed test and novel object recognition test, two commonly applied assays for exploratory activity, locomotor, learning, and memory ability." (PMID 34132500, 2021). "Thus, plasma concentrations of total BDNF were significantly lower in patients with cognitive impairment than in patients without cognitive impairment." (PMID 34341419, 2021). "In addition, melatonin and resveratrol can improve the BDNF expression in the hippocampus of bilateral common carotid artery occlusion (BCCAO)-treated rats, resulting in an improvement in cognitive deficits as tested by the Morris water maze and novel object recognition tests." (PMID 33923672, 2021). "Previous studies have reported decreases in the phosphorylation levels of Akt and CREB, as well as in the expression of BDNF, in the hippocampus of CCH rats, which suggests that this signaling pathway may be involved in the development of cognitive impairment in these rats." (PMID 34211568, 2021). "Therefore, this study aimed to examine whether BDNF activation by HDACi may affect the protein levels of AMPA and dopamine receptors under CCH conditions, thus leads to attenuation of cognitive impairment." (PMID 34216182, 2021). "However, one recent study showed that prolonged exposure of postnatal day 7 (P7) rat pups to ketamine (20 mg/kg per dose) decreased BDNF expression and the phosphorylation of AKT and ERK and increased apoptosis in the developing rat hippocampus, which corresponded with later cognitive impairments." (PMID 34566558, 2021). "OPP given to mice up-regulated genes involved in brain development under the regulation of brain-derived neurotrophic factor (BDNF) and down regulated genes related to inflammation suggesting a mechanism by which OPP may improve memory and reduce cognitive impairment." (PMID 33808068, 2021). "Despite the fact that BDNF has been known to possess a protective effect on the brain, an elevated BDNF level did not protect our participants from cognitive impairment due to acute exposure to hypoxia, because indices of this variable, i.e., CRT and NCR, were worse in hypoxic conditions." (PMID 32759658, 2020). "In addition, melatonin enhances BDNF and CREB, alleviating cognitive impairment." (PMID 32731545, 2020). "In addition to drug delivery, both involuntary exercise induced by functional electrical stimulation and voluntary exercise increased the number of BDNF‐positive cells in the hippocampal CA1, CA2, CA3, and dentate gyrus regions and alleviated cognitive deficits in ischemic rats." (PMID 32374084, 2020). "Thus, the increase in BDNF levels, the decrease in S100B, and the absence of cognitive deficit can be explained by the potentiation of this pathway." (PMID 33019732, 2020). "COX5A overexpression rescued the repression of the BDNF/ERK1/2 pathway, which is in line with the results presented in previous studies, thereby indicating that the BDNF/ERK1/2 pathway is a molecular therapeutic pathway in the treatment of cognitive impairment in Tg AD mice." (PMID 32754029, 2020).